SOCS3 (suppressor of cytokine signaling 3)
Diseases named in the same sentence as SOCS3 in open-access papers (continued):
Sharing a sentence is not in itself a finding about the gene and the disease.
Insulin resistance (continued). "In the leptin- and insulin-related pathways, PTP1B and SOCS3 are negative regulators and make major contributions to leptin and insulin resistance." (PMID 31344867, 2019). "Obesity-induced hyperleptinemia enhances SOCS3 expression, resulting in hypothalamic insulin resistance." (PMID 30875909, 2019). "Further study is warranted to determine the specific relationship between SOCS3 and insulin resistance." (PMID 29973864, 2018). "SOCS3 is also involved in neroninflammation and is essential for inflammation-regulated insulin resistance in the central." (PMID 29973864, 2018). "It was also found that serum progranulin contributes to developing insulin resistance through increasing IL-6, which in turn, impairs insulin signaling by stimulating SOCS3 expression." (PMID 30096951, 2018). "Note, SOCS2 deletion was shown to protect against hepatic steatosis but worsens insulin resistance in high-fat-diet-fed mice while ablation of SOCS3 enhances hepatic insulin sensitivity but increases lipogenesis resulting in fatty liver and obesity." (PMID 30547786, 2018). "Both SOCS1 and SOCS3 have been attributed to the development of insulin resistance by inhibiting the phosphorylation of IRS1 and IRS2 proteins." (PMID 29025435, 2017). "Socs3 has been reported to be highly expressed in the obese liver, and to bind to the insulin receptor, inducing insulin resistance." (PMID 28870184, 2017). "The upregulation of SOCS1 and SOCS3 has been projected as a mechanism for imparting insulin resistance by the downregulation of IRS1." (PMID 29025435, 2017). "Next, we analyzed the expression of known negative regulators (i.e., C/EBPβ, HDAC4 and PTEN) of insulin sensitivity and known inducers (i.e., SOCS1 and SOCS3) of insulin resistance." (PMID 27711113, 2016). "SOCS3 is a major negative regulator of insulin and leptin signaling and is thought to contribute to the pathogenesis of insulin resistance." (PMID 27337171, 2016). "Pio reduced TNF-α and SOCS3-activated insulin resistance pathways in the retina and protected against diabetic retinopathy." (PMID 26336514, 2015). "In the present study, we did not report any significant difference in protein expression of TNF-alpha, IL-6 and SOCS3 during HFD-induced cardiac insulin resistance." (PMID 26539824, 2015). "In continuation of our work on TNFα-induced retinal insulin resistance, we measured SOCS3 and IRTyr960 in the BBZDR/Wor lean and obese rats alone and treated with salicylate." (PMID 25874611, 2015). "SOCS-3 is overexpressed during insulin resistance, thereby inducing SREBP-1 epxression, which is involved in the homeostatic regulation of lipid levels." (PMID 26046125, 2015). "Adipocyte-derived IL-6 was shown to regulate hepatic insulin resistance via upregulation of suppressor of cytokine signaling 3 (SOCS3) which in turn induces an increase in SREBP-1c and DNL." (PMID 26090470, 2015). "Based on prior work demonstrating that TNFα activates SOCS3 and SOCS3 can induce insulin resistance through activation of insulin receptor via phosphorylation on tyrosine 960, we measured both SOCS3 and IRTyr960 in the lean and obese animals." (PMID 25874611, 2015). "SOCS3 induces insulin resistance through increased phosphorylation of the insulin receptor on tyrosine 960, which inhibits the insulin receptor/IRS-1 interaction." (PMID 25874611, 2015). "Data demonstrated that salicylate significantly improved retinal function, as well as reduced TNFα and SOCS3-induced insulin resistance in all samples." (PMID 25874611, 2015). "miR-15b and miR-16 play a role in the inhibition of insulin resistance via reduced TNFα and SOCS3 signaling and increased IGFBP-3 levels, resulting in REC protection from hyperglycemia-induced apoptosis." (PMID 25888955, 2015).
Insulin resistance (continued). "Taken together, these results demonstrate that miR-15b and miR-16 play a role in the inhibition of insulin resistance via reduced TNFα and SOCS3 signaling and increased IGFBP-3 levels, resulting in REC protection from hyperglycemia-induced apoptosis." (PMID 25888955, 2015). "Recent studies have shown that holo-RBP/STRA6 is involved in the regulation of activation of the JAK2/STAT5 cascade and insulin resistance, by inducing the suppressor of cytokine signaling 3 (SOCS3) and PPARγ expression." (PMID 26237391, 2014). "Exogenous SOCS3 reduced Akt phosphorylation, leading to increased cleaved caspase 3 levels, suggesting that SOCS3 acts to promote insulin resistance." (PMID 25352752, 2014). "This evidence suggests that insulin resistance in CUG-SGA rats is associated with impairment of IRS-1-PI3K-AKT signaling, which results from GHR signaling-induced upregulation of SOCS3 expression." (PMID 24963636, 2014). "SOCS3 is a major negative regulator of insulin and leptin signaling, which is thought to contribute to the pathogenesis of insulin resistance." (PMID 23846596, 2013). "In adipose tissue and liver, however, IL-6 will exert proinflammatory activities, increasing insulin resistance by upregulating SOCS3 (suppressor of cytokine signaling 3) which, in turn, impairs insulin-induced insulin receptor and IRS1 phosphorylation." (PMID 24455420, 2013). "Chronically elevated IL-6 levels in obesity have been considered to contribute to systemic insulin resistance by inducing the expression of suppressor of cytokine signaling 3 in adipose tissue and liver." (PMID 23555753, 2013). "In the same way, targeted invalidation of SOCS3 in adipose tissue or in muscles protected mice against obesity-induced insulin resistance." (PMID 23316186, 2012). "In contrast, while targeted deletion of SOCS3 in liver-enhanced liver insulin sensitivity on chow diet, it accelerated the onset of high-fat diet- or age-induced insulin resistance with an increased inflammation in liver." (PMID 23316186, 2012). "In summary, we demonstrate that muscle-specific over-expression of SOCS3 impairs muscle insulin signaling and promotes systemic insulin resistance." (PMID 23115649, 2012). "SOCS3 is increased in inflammation and is thought to contribute to the pathogenesis of insulin resistance by inhibiting insulin signaling." (PMID 22761701, 2012). "Muscle SOCS3 is therefore positioned to play an important role in the pathogenesis of obesity-induced insulin resistance and type 2 diabetes by antagonizing both leptin and insulin signaling in skeletal muscle." (PMID 23115649, 2012). "Unexpectedly, overexpression of SOCS3 in adipose tissue protected the mice against systemic insulin resistance when fed a high-fat diet owing to a decrease in adipocyte hypertrophy." (PMID 23316186, 2012). "Overexpression of the suppressor of cytokine signaling 3 in adipocytes equally results in local insulin resistance despite increasing whole body glucose tolerance." (PMID 23024762, 2012). "In contrast, our current genetic model with muscle SOCS3 over-expression demonstrates a prominent role for muscle SOCS3 in the development of systemic insulin resistance in obesity." (PMID 23115649, 2012). "Our study suggests that SOCS3 within skeletal muscle is a critical factor in the development on of both skeletal muscle-specific and systemic insulin resistance in response to obesity." (PMID 23115649, 2012). "To further evaluate the contribution of muscle SOCS3 to leptin and insulin resistance in obesity, we generated transgenic mice with muscle-specific overexpression of SOCS3 (MCK/SOCS3 mice)." (PMID 23115649, 2012). "Brain-specific SOCS-3 knockout mice showed elevated leptin sensitivity, were resistant to high fat diet induced obesity and had attenuated insulin resistance." (PMID 21955513, 2011). "In vivo, Adenoviral overexpression of SOCS1 or SOCS3 in the liver enhances insulin resistance and fatty acid synthesis." (PMID 20862390, 2010).
Insulin resistance (continued). "Additionally, IL-6 induces SOCS3-mediated insulin resistance, resulting in a diminished energy supply to muscles and facilitating the accumulation of free fatty acids (FFA), which further exacerbates muscle damage." (PMID 40255379, 2025). "Additionally, TNF-α and IL-6 contribute to hepatic insulin resistance through upregulation of Suppressor of Cytokine Signaling 3 (SOCS3)." (PMID 41472723, 2025). "Furthermore, STAT3 inhibits the phosphorylation of insulin receptor substrates (IRS) by up-regulating SOCS3, exacerbates insulin resistance, and forms a vicious cycle of metabolism and inflammation." (PMID 41226680, 2025). "Moreover, STAT’s target gene is SOCS3, which inhibits insulin receptor signaling, which also results in insulin resistance." (PMID 41007818, 2025). "In hepatic metabolic regulation, PGE2 from Kupffer cells may affect liver insulin resistance by disrupting SOCS3, which decreases insulin-driven glucose use." (PMID 40969371, 2025). "Additionally, miR‐152 has been shown to improve hepatic insulin resistance in gestational diabetes mellitus (GDM) mouse models by downregulating SOCS3 expression." (PMID 40309956, 2025). "Inhibiting SOCS3 to ameliorate immune homeostasis, inflammation, and metabolic issues, such as leptin and insulin resistance, might be a promising therapeutic approach." (PMID 40104138, 2025). "Moreover, the neuron-specific deletion of SOCS3 protected against diet-induced obesity, leptin resistance, and insulin resistance." (PMID 40690443, 2025). "Mechanistically, increased TSH levels in subclinical hypothyroidism promoted the secretion of cytokines IL-1α, IL-1β and IL-6 by inducing macrophage M1 polarization, which upregulated EGR1 to transcriptionally activate LCN2 and SOCS3 in insulin target cells, thereby exacerbating insulin resistance." (PMID 40523992, 2025). "The increased expression of SOCS3 may induce the development of insulin resistance by inhibiting the JAK/STAT3 signaling pathway." (PMID 39596180, 2024). "In OAT, SOCS3 was correlated with insulin resistance and transaminase enzymes (p < 0.05 for all." (PMID 38928125, 2024). "In vitro studies also showed that overexpression of SOCS3 in adipocytes can cause local insulin resistance in adipocytes but not enough to cause systemic insulin resistance." (PMID 39596321, 2024). "SOCS3 inhibits insulin signaling and leads to the development of insulin resistance." (PMID 36609306, 2023). "Knockout of the FGF21 gene in liver tissue can activate glucose-6-phosphatase and phosphoenolpyruvate carboxykinase through STAT3/SOCS3 pathway, thus increasing gluconeogenesis and glycogen decomposition, resulting in the aggravation of liver insulin resistance." (PMID 36982739, 2023). "Moreover, mRNA expression of SOCS1 and SOCS3 in SAT was associated with known obesity indices, insulin resistance, and hs-CRP, suggesting the contribution of SOCS1 and SOCS3 in the pathogenesis of obesity-related metabolic abnormalities." (PMID 36609306, 2023). "However, the possible stimulatory role of insulin resistance, hyperinsulinemia, and inflammation in the induction of SOCS3 expression cannot be ignored." (PMID 36609306, 2023). "Overexpression of SOCS3 in liver tissues induces insulin resistance." (PMID 35052633, 2022). "Thus, resistin induces insulin resistance and impairs insulin secretion in pancreatic beta cells via the increased expression of suppressor of cytokine signaling 3 (SOCS-3) and reduced AKT phosphorylation." (PMID 35634505, 2022). "In a previous study, the effect of SOCS3 on insulin resistance in mouse livers was investigated." (PMID 36078084, 2022). "SOCS3 also mediates insulin resistance and elevated SOCS3 levels, as shown here in aged mice, may predispose to neurodegenerative diseases." (PMID 36497123, 2022).
Insulin resistance (continued). "This notion was further supported by who showed that inactivation of SOCS3 in LepR-expressing cells protects mice against diet-induced insulin resistance, indicating that SOCS3 is a critical downstream signaling mediator of leptin to orchestrate glycemic control." (PMID 33935782, 2021). "In addition, suppressor of cytokine signaling 3 (SOCS3) has been identified to have an emerging role linking central insulin resistance and Alzheimer’s disease, but the relationship between SOCS3 and stroke has not been studied sufficiency." (PMID 32228489, 2020). "The effects on the offspring observed in this study from 1000 mGy whole-body irradiations on the dams, suggest that a one-time SLDR causes physiological changes in metabolic activity in the female liver based on increases in protein expression of targets of insulin resistance, SOCS3 and PEPCK." (PMID 32315370, 2020). "In models of insulin resistance, SOCS3 protein expression is elevated in the liver." (PMID 32315370, 2020). "Most prominently, female offspring from 1000 mGy dams showed increased expression of genes which contribute to insulin resistance and gluconeogenesis (PPARG1a/b, SOCS3 and PEPCK) at 4 months of age, while genes involved in glucose metabolism were unaffected (GSK, IRS1, GLUT2)." (PMID 32315370, 2020). "These markers located in ABCG1, PHOSPHO1, SOCS3, SREBF1, and TXNIP were associated with metabolic measures of insulin resistance including glucose concentration, BMI, waist-to-hip ratio, and homeostatic model assessment for insulin resistance (HOMA-IR)." (PMID 32211026, 2020). "From our results, female SOCS3 expression increased in offspring of dams that were exposed to 1000 mGy of radiation suggesting the presence, or perhaps an early indicator, of insulin resistance." (PMID 32315370, 2020). "In addition, H. pylori infection induced insulin resistance in hepatocytes by activating the c-Jun/miR-203/SOCS3 signaling pathway." (PMID 33013895, 2020). "Furthermore, the expression of SOCS3 in skeletal muscle, which can aggravate insulin resistance, was reduced by nCrPic." (PMID 32961883, 2020). "Similarly, PPARβ/δ represses IL-6-induced STAT3 activation and suppressor of cytokine signaling-3 (SOCS-3) upregulation in human liver cells and thereby halts the development of insulin resistance." (PMID 32708786, 2020). "By their ability to promote ubiquitination and proteasomal degradation of insulin receptor substrates 1 and 2 (IRS1, IRS2), which link RTK signaling to PI3K, SOCS1 and SOCS3 can regulate AKT activation in the context of insulin resistance in the liver and other organs." (PMID 32807134, 2020). "Moreover, hepatic PPARγ reduces the expression of SOCS-3, which has been suggested to play a crucial role in linking inflammation and hepatic insulin resistance." (PMID 32708786, 2020). "Thus, SOCS3 was a good candidate to negatively regulate insulin signaling at early time-points, prior to the delayed (7 days) insulin resistance that we found." (PMID 31160730, 2019). "Localized increases of suppressor of cytokine signaling 3 (SOCS3), known as an inhibitor of leptin and insulin signaling specifically in the hypothalamus, may lead to leptin and insulin resistance." (PMID 29498693, 2018). "Based on these findings, it is reasonable to speculate that SOCS3 is involved in the development of insulin resistance in the human body and that increased levels of SOCS3 could lead to pathological conditions that disrupt the insulin signaling pathway." (PMID 29973864, 2018). "Moreover, increased SOCS1/SOCS3 expression during uveitis induces insulin resistance in neuroretina, and SOCS3 overexpression is responsible for the induction of insulin resistance in mice infected with hepatitis C virus." (PMID 30116482, 2018). "As SOCS3 has also been identified in peripheral tissues, we speculate that SOCS3 plays an essential role in the establishment of insulin resistance in AD." (PMID 29973864, 2018).
Insulin resistance (continued). "Increased proinflammatory cytokines can trigger insulin resistance by several mechanisms, including activation of SOCS3 expression and/or the activation of numerous intracellular serine kinases such as jun N-terminal kinase (JNK) and inhibitor of κB kinase (IKK)." (PMID 28771483, 2017). "However, inactivation of SOCS3 in ObRb-expressing cells protects mice from diet-induced insulin resistance, indicating that the regulation of leptin signaling by SOCS3 orchestrates diet-induced changes on glycemic control." (PMID 28270795, 2017). "Induction of SOCS3 and reduction of oxytocin expression might explain leptin and insulin resistance as well as hyperphagia that are observed in CMHL rats already 7 d post-surgery and that are also key clinical features in CP patients." (PMID 27512604, 2016). "Moreover, numerous factors mediating the pathophysiology of leptin resistance, a hallmark of obesity, such as endoplasmic reticulum stress, protein tyrosine phosphatase 1B, and suppressor of cytokine signaling 3 also contribute to insulin resistance." (PMID 27812350, 2016). "In addition, inflammation induced upregulation of SOCS-3, a marker of leptin and insulin resistance, can result in impaired ability of satiety signals, such as cholecystokinin, to activate neurons in the hindbrain and reduce food intake." (PMID 27512604, 2016). "Therapies aimed at inhibiting SOCS3 in skeletal muscle may help reverse glucose intolerance and insulin resistance." (PMID 27337171, 2016). "In addition to TNFα actions on IRS-1, TNFα also can activate other proteins known to be involved in insulin resistance, namely suppressor of cytokine signaling 3 (SOCS3)." (PMID 25874611, 2015). "To test our hypothesis, we treated wildtype mice or β2KO mice with etanercept for two months and measured proteins involved in insulin resistance and signaling, including TNFα, SOCS3, insulin receptor (IR), and apoptotic markers." (PMID 25138272, 2014). "Increases in TNF-α and SOCS3 are triggered by high glucose and through reciprocal stimulation of expression of these two factors, which in turn could be major drivers of insulin resistance and related cell death." (PMID 25352752, 2014). "Additionally, we demonstrated in retinal endothelial cells that TNFα activation of SOCS3 and IRS-1Ser307 leads to decreased insulin signal transduction, which likely underlies insulin resistance." (PMID 24695399, 2014). "Finally, another master regulator of hepatic lipogenesis, mTORC1, not only induces lipogenic activity but can potentiate insulin resistance via stimulation of SOCS3 expression, which can also stimulate lipogenesis via SREBP1." (PMID 25937836, 2014). "Increases in TNF-α and SOCS3 are triggered by high glucose and through reciprocal stimulation of the expression of these two factors, which in turn could be major drivers of insulin resistance and related cell death." (PMID 25352752, 2014). "Insulin resistance in CUG-SGA rats is associated with impairment of IRS-1-PI3K-AKT signaling, which may result from GH signaling-induced up-regulation of SOCS3." (PMID 24963636, 2014). "Thus, TNF-α and SOCS3 require an active serine 307 phosphorylation site on IRS-1 to bring about insulin resistance." (PMID 25352752, 2014). "Moreover, insulin resistance in CUG-SGA rats is associated with impairment of the IRS-1-PI3K-AKT signaling pathway, which results from GH signaling-induced upregulation of SOCS3 expression." (PMID 24963636, 2014). "Also, have been shown that TNF-α and IL-6 cause systemic insulin resistance through activation of MAP kinases, protein kinase C (PKC) and SOCS-3 mediated proteasome degradation." (PMID 24966877, 2014). "In particular, the induction of SOCS3 in liver may be an important mechanism of IL-6-mediated insulin resistance." (PMID 23861927, 2013). "Therapies aimed at inhibiting SOCS3 in skeletal muscle may be a favorable strategy to reverse glucose intolerance and insulin resistance." (PMID 23846596, 2013).